GSK3B (glycogen synthase kinase 3 beta)
Diseases named in the same sentence as GSK3B in open-access papers (continued):
Sharing a sentence is not in itself a finding about the gene and the disease.
lung adenocarcinoma (35 papers, 2012 to 2026). A carcinoma that arises from the lung and is characterized by the presence of malignant glandular epithelial cells. "SRSF1 and GSK3B were filtered through “overall survival”, and high expression was associated with a poorer prognosis than low expression in a subset of lung adenocarcinoma patients." (PMID 36523489, 2022). "This study investigated the correlation between GSK-3β expression and clinically relevant molecular features of lung adenocarcinoma (PDL1 score, PTEN expression and driver mutations)." (PMID 33767989, 2021). "Loss of SARI and E-cadherin and increased vimentin, p-GSK-3β, and β-catenin levels were clearly detected in tissues from lung adenocarcinoma patients with lymph node metastasis." (PMID 23049725, 2012). "Loss of SARI and E-cadherin and increased vimentin and p-GSK-3β were clearly detected in tissues from lung adenocarcinoma patients who had lymph node metastasis." (PMID 23049725, 2012). "Another study also investigated the progression of lung adenocarcinoma by activating AKT/GSK‐3β signalling and regulating apoptosis via mitochondrial pressure." (PMID 39160643, 2024). "Among these targets, GSK3B had a significant effect on lung adenocarcinoma patients, and the statistical analysis of the effect on squamous lung cancer patients was not very significant." (PMID 38017514, 2023). "We analyzed the prognostic impact of PKC, PAK1, and GSK3B in patients with lung adenocarcinoma and squamous lung cancer." (PMID 38017514, 2023). "Our finding is corroborated by our immunohistochemical analysis with tissue microarray demonstrating the negative correlation between hnRNPK expression level and that of the Ser9-phsphorylated GSK3β in lung adenocarcinoma tissues." (PMID 26972480, 2016). "In lung adenocarcinoma cells, lncRNA bound to GSK-3β, thereby regulating the function of GSK-3β." (PMID 36851033, 2023). "After treatment with the PI3K inhibitor and EGF, the expression of Snail decreased, indicating that LncRNA-AC009948.5 could promote Snail nuclear metastasis in lung adenocarcinoma cells through the PI3K/Akt/GSK3β signaling pathway." (PMID 36059662, 2022). "Hence, LncRNA-AC009948.5 can promote Snail nuclear metastasis in lung adenocarcinoma cells through the PI3K/Akt/GSK3β signaling pathway and consequently the occurrence of EMT." (PMID 36059662, 2022). "The PI3K/Akt/GSK3β signaling pathway is related to EMT in lung adenocarcinoma cells." (PMID 36059662, 2022). "After treatment with the PI3K inhibitor and EGF, the expression levels of E-cadherin and Vimentin recovered, indicating that LncRNA-AC009948.5 could promote EMT in lung adenocarcinoma cells through the PI3K/Akt/GSK3β signaling pathway." (PMID 36059662, 2022). "Further, Zeng and his colleagues demonstrated MGST1 knockdown could inhibit lung adenocarcinoma cell proliferation by inactivating the AKT/GSK-3β pathway signaling and promote cell apoptosis by regulating the mitochondrial apoptosis pathway related proteins." (PMID 33014847, 2020). "The results showed that hnRNPK was highly overexpressed in both the nucleus and cytoplasm of lung adenocarcinoma cells as compared with normal tissues, whereas the phospho-GSK3β was mainly located in the cytoplasm which was significantly downregulated in the tumor tissues." (PMID 26972480, 2016). "Our immunohistochemical analysis using tissue microarray provides the clinical evidence of this finding by establishing a negative correlation between the level of hnRNPK expression and the Ser9 phosphorylation of GSK3β in both lung adenocarcinoma tissues and normal tissues." (PMID 26972480, 2016). "In addition, after knockout of GSK3β, the protein level of β-catenin was inconsistent in the lung adenocarcinoma cells, suggesting that in NSCLC cells, the expressions of β-catenin is regulated in a cell-type specific manner." (PMID 24618715, 2014).
lung adenocarcinoma (continued). "In several tested lung adenocarcinoma cell lines, we showed that GSK-3β S9 phosphorylation was clearly involved in SARI-mediated β-catenin stability and transcriptional activity, suggesting that the effect of S9 phosphorylation on β-catenin signaling is cell-type dependent." (PMID 23049725, 2012). "A signaling pathway involving EGFR, ErbB2, ErbB3, phosphatidylinositol 3-kinase (PI3K), Akt, glycogen synthase kinase 3- β (GSK3-β), and cyclin D1 is essential for the maintenance of survival, mitosis, and invasiveness of human lung adenocarcinoma cell lines as well as to evade apoptosis." (PMID 22724003, 2012). "Knockdown of MGST1 inhibits lung adenocarcinoma cell proliferation and induces apoptosis via inactivation of the AKT/GSK-3β signaling pathway." (PMID 40778224, 2025). "In lung adenocarcinoma, BZW2 promotes tumor malignant progression by enhancing the ubiquitination and degradation of GSK3β." (PMID 40413536, 2025). "Researchers have also explored the role of circ-GSK3B, a circular RNA, in lung adenocarcinoma (LUAD), investigating its connection with glycogen synthase kinase 3 beta (GSK3B) and the Wnt/β-catenin signaling pathway." (PMID 40070571, 2025). "It has been reported that dioscin, a therapeutic agent for lung adenocarcinoma, can suppress the proliferation, invasion and EMT of lung cells via the inactivation of AKT/mTOR/GSK3β signaling pathway." (PMID 40768543, 2025). "To establish the clinical relevance of increased PIM1/GSK3β signaling in mediating acquired resistance to osimertinib in NSCLC, we obtained CT images of three cases of advanced EGFR-mutant lung adenocarcinoma." (PMID 39227379, 2024). "In lung adenocarcinoma, MTHFD2 promoted cell growth and metastasis via AKT/GSK‐3β/β‐catenin signalling." (PMID 37480214, 2023). "Recently, it was reported that ZNF185 expression is negatively correlated with lymph node metastasis of lung adenocarcinoma and its overexpression leads to down-regulation of p-AKT, p-GSK3β, VEGF and MMP-9 expression." (PMID 30446632, 2018). "In this study, we show that, when H1299 lung adenocarcinoma cells are treated with TRAIL, hnRNPK is translocated from nucleus to cytoplasm where it interacts and co-localizes with GSK3β." (PMID 26972480, 2016). "Accordingly, MCME, although not fully elucidated, may suppress lung adenocarcinoma cell invasion by inhibiting the expression of MMPs through the regulation of Src, FAK, PI3K/Akt, GSK-3β, and β-catenin." (PMID 23320038, 2012).
Stroke (34 papers, 2011 to 2026). Sudden impairment of blood flow to a part of the brain due to occlusion or rupture of an artery to the brain. "FKBP51 also regulates signaling pathways such as NF-κB, Akt, and GSK3β through its scaffolding functions—pathways closely linked with stress, metabolic syndrome, and stroke-related pathophysiology." (PMID 41091275, 2025). "In conclusion, this study demonstrated that OA administration can prevent stroke-associated pathological changes by inducing antioxidative effects via regulating the GSK-3β/HO-1 pathway both in vitro and in vivo." (PMID 35056059, 2021). "NBP promotes post‐stroke angiogenesis by upregulating VEGF through activation of the Akt/GSK3β pathway." (PMID 41373119, 2025). "Collectively, these results demonstrate that NBP facilitates post‐stroke angiogenesis, vasodilation, and functional restoration through Akt/GSK‐3β pathway activation." (PMID 41373119, 2025). "Emerging evidence indicates that drugs targeting the Akt/GSK‐3β/β‐catenin signaling pathway enhance post‐stroke angiogenesis and facilitate functional recovery." (PMID 41373119, 2025). "This study presents the first demonstration that NBP promotes post‐stroke angiogenesis and functional recovery through Akt/GSK‐3β‐mediated VEGF upregulation." (PMID 41373119, 2025). "Since GSK‐3β is concentrated in the central nervous system, GSK‐3β activity disorder can lead to the occurrence and development of various nervous system diseases, such as stroke, neurodegenerative diseases (AD), epilepsy, and spinal cord injury." (PMID 39129397, 2024). "The objective of this study was to explore the protective mechanism of 1,25-D3 against brain injury and to determine the role of AMPK/AKT/GSK-3β signaling in this process, thus allowing us to determine the therapeutic potential of 1,25-D3 in stroke." (PMID 36325190, 2022). "We only investigated the effect of 1,25-D3 on the AMPK/AKT/GSK-3β pathway in mediating mitochondrial apoptosis, and other pathways in stroke should be studied in subsequent experiments." (PMID 36325190, 2022). "Up-regulation of GSK-3β activity after stroke can result in cell death and aberrant neuronal migration in primary neuronal populations." (PMID 33299813, 2020). "In contrast, candesartan administration in permanent stroke model significantly reduced Akt and GSK3-β activity." (PMID 27127602, 2016). "In the chronic state, GSK-3β inhibitors promote neurovascular remodeling after stroke and improve postischemic stroke sequelae." (PMID 21603026, 2011). "In stroke, GSK-3β has been reported to be involved in neuronal cell death, whereas treatment with GSK-3β inhibitors in the acute state reduces infarction volume and improves neurobehavioral function." (PMID 21603026, 2011). "Given its established neuroprotective roles, we hypothesized that NBP may also facilitate post‐stroke angiogenesis through the Akt/GSK‐3β pathway, a key regulator of vascular remodeling." (PMID 41373119, 2025). "Similarly, miR-17-92 cluster-enriched MSC-Exos increase functional recovery and neural plasticity after stroke possibly by targeting PTEN to activate the phosphatidylinositol-3-kinase (PI3K)/Akt/mTOR/glycogen synthase kinase 3 beta (GSK-3β) signaling pathway." (PMID 34070696, 2021). "Additionally, TWS119 enhanced the level of β-catenin via inhibiting GSK-3β at day 14 after stroke and mitigated the histological damage of focal cerebral ischemic mouse at day 21 after stroke." (PMID 31810470, 2019). "Therefore, inactivation of GSK-3β could serve as a novel therapeutic target for the protection of stroke and this needs further studies." (PMID 33935731, 2021). "Moreover, inhibition of GSK-3β attenuates early stroke injury in a focal ischemic model." (PMID 35002691, 2021). "To elucidate the role of the Akt/GSK‐3β pathway in NBP‐induced cerebrovascular repair and recovery, we administered LY294002 in the stroke model." (PMID 41373119, 2025).
Stroke (continued). "Current evidence indicates that NBP promotes post‐stroke angiogenesis through multiple pathways, including Shh and HIF‐1α/VEGF signaling, however, the involvement of the Akt/GSK‐3β/β‐catenin pathway remains to be elucidated." (PMID 41373119, 2025). "Experiments have shown that GSK-3β inhibitor TWS119 can effectively reduce the volume of cerebral infarction and improve neuroinflammation in the chronic phase of experimental stroke." (PMID 40842649, 2025). "Lithium, an inhibitor of GSK-3β, activates mTOR through the Wnt/GSK-3β pathway, inhibits autophagy, and improves ischemic brain damage in the MCAO rat model of stroke." (PMID 38792655, 2024). "In particular, PKG has been shown to be an important target for protection against stroke, it can regulate CREB, GSK-3β and other proteins to reduce autophagy and apoptosis-induced neuronal damage after AIS." (PMID 36180911, 2022). "Moreover, it has been shown that GSK3β interacts with RIPK1 molecules to promote RIPK1 molecular activity and promote post-stroke scar formation, leading to poor prognosis." (PMID 37443080, 2023). "GSK-3β inhibition can reduce the BBB damage and early ischemia/reperfusion injury in stroke." (PMID 35359227, 2022). "Additionally, isorhamnetin protects against rotenone-induced neurotoxicity in pc12 cells through modulation of the PI3K/Akt/GSK-3β/CREB pathway, which may contribute to neuronal survival and synaptic plasticity in stroke-affected regions." (PMID 40277696, 2025). "For instance, lithium application promotes neuroplasticity and recovery after stroke in rats, which upregulated the expression of VEGF to promote endothelial cell proliferation and maintain blood-brain barrier homeostasis through PI3K/GSK3β-dependent and -independent pathways." (PMID 35321503, 2022). "Our results are consistent with previous findings in experimental stroke that showed that phosphorylation levels of factors downstream of Akt, such as Bad and GSK3β, do not increase together with p-Akt; rather, both of them decrease when p-Akt Ser 473 increases." (PMID 23029230, 2012).
Sepsis (32 papers, 2012 to 2025). Sepsis is defined as life-threatening organ dysfunction caused by a dysregulated host response to infection. "Bioinformatics studies have shown that GSK-3β is a core target associated with inflammatory chemotaxis in sepsis, and its expression is positively correlated with neutrophil chemotaxis, which is the main anti-inflammatory target of LGS." (PMID 37456759, 2023). "Key machine algorithm and LAASO regression analysis identified 1 HUB gene, confirming GSK-3β as a signature gene associated with inflammatory chemotaxis in sepsis." (PMID 37456759, 2023). "In addition, the AUC result was 0.963 (95% CI 0.941–0.982), suggesting that GSK-3β has superior performance in predicting sepsis and can be used as a diagnostic marker." (PMID 37456759, 2023). "This makes GSK3β another potential target for sepsis-associated brain injury." (PMID 35488237, 2022). "In the current study, we showed that GSK‐3β was associated with cardiac dysfunction during sepsis, and its inhibition attenuated the LPS‐induced inflammation injury mediated by negatively regulating ERK/NF‐κB pathway and promoted AMPK signalling in LPS‐induced sepsis." (PMID 31503410, 2019). "Finally, we screened out the signature gene GSK-3β, which is associated with inflammatory chemotaxis in sepsis, and demonstrated that the anti-septic effects of LGS in vitro and in vivo through meddling in GSK-3 β expression to regulate leukocytes migration and polarization." (PMID 37456759, 2023). "Expression of glycogen synthase 1 (Gys1) was upregulated in acute and prolonged sepsis, whereas expression of regulator glycogen synthase kinase (Gsk3b) or glycogen phosphorylase (Pygb) were not affected." (PMID 39821755, 2025). "Previous studies have established that glycogen metabolism modulates inflammatory signaling during sepsis largely through GSK3β activity, which integrates upstream signals to regulate transcriptional responses via NF-κB and CREB pathways." (PMID 41333476, 2025). "Inducing GSK-3β phosphorylation inactivation inhibits sepsis-induced cardiac dysfunction and mitochondrial dysfunction." (PMID 37456759, 2023). "Upon evaluation, the receiver operating characteristic (ROC) curve of GSK-3β indicated an important role in the pathogenesis of sepsis." (PMID 37456759, 2023). "GSK3β is a central kinase in inflammation, and the benefits of inhibiting this enzyme have been demonstrated in studies of sepsis and organ failure." (PMID 36904071, 2023). "GSK3β inhibitors reduced the severity of sepsis and improved survival in experiments in models of acute lung injury." (PMID 36904071, 2023). "In a rat model of sepsis, the combination of selective GSK3β blockers reduced LPS-induced liver failure and injury." (PMID 36904071, 2023). "Further studies are needed to understand how GSK3β activity is dysregulated in the pathogenesis of sepsis and host immune responses to pathogens." (PMID 36904071, 2023). "Oleuropein attenuates sepsis-induced systemic inflammation and myocardialinjury by inhibiting NF-kB and GSK-3β signaling." (PMID 33605309, 2021). "HBOT appears to reduce hyperinflammatory reactions through modifying cell signaling in this sepsis model; however, the anti-apoptotic mechanism involving Akt activation and GSK-3β inhibition needs further investigation." (PMID 33203111, 2020). "Despite GSK-3β inhibitor is recognized as a potential treatment of sepsis, our data demonstrated that many components of canonical Wnt3a signaling were also affected in the lung of rats with endotoxic shock." (PMID 26218875, 2015). "We aimed to investigate the protective effects of GSK-3β inhibition on polymicrobial sepsis-induced liver injury and to explore the possible mechanisms." (PMID 25525303, 2014). "GSK-3β is known to regulate NF-κB signaling, which plays a pivotal role in the pathophysiology of sepsis." (PMID 25525303, 2014). "GSK-3β inhibitors also provide a survival advantage and can attenuate organ injury in animal models of sepsis." (PMID 23533310, 2013).